ARHGAP11A-SCG5 (ARHGAP11A-SCG5 readthrough)
Gene: Protein-coding gene on chromosome 15 (32,613,860 to 32,697,095, forward strand). Ensembl gene ENSG00000288864.
Genetic constraint (gnomAD): Loss-of-function variants: 35 observed, 57.25 expected, observed/expected ratio (o/e) 0.61, 90% interval 0.47 to 0.81. The upper end of that interval is the gene's LOEUF score, 0.81, which puts it in group 3 of 6, group 1 being the genes least tolerant of losing a copy. Missense variants: 480 observed, 672.14 expected, observed/expected ratio (o/e) 0.71, 90% interval 0.66 to 0.77. Synonymous variants: 214 observed, 238.03 expected, observed/expected ratio (o/e) 0.9, 90% interval 0.8 to 1.01.